HLA-C (major histocompatibility complex, class I, C)
Diseases named in the same sentence as HLA-C in open-access papers (continued):
Sharing a sentence is not in itself a finding about the gene and the disease.
infection (continued). "This indicates that the KF9 epitope is still an immunodominant epitope in HLA-C*12:02+ convalescent donors even at 6 months after infection." (PMID 40877317, 2025). "The KIR2DL2 and KIR2DS2 receptors appear to play a key role in the susceptibility and severity of the infection, particularly when KIR2DL2 is combined with HLA-C." (PMID 40244151, 2025). "HLA-C is a class I major histocompatibility complex (MHC-I) molecule involved in the immune surveillance against infections and malignancies." (PMID 41459481, 2025). "Of the variables examined, increased size of HLA-C peptide binding repertoire predicts poor response to infection (coefficient = 1.41 ± 0.58)." (PMID 39337964, 2024). "HCMV sero-positivity was shown to dramatically alter the maternal CD8+ T cell repertoire during pregnancy and similar to HIV, T cell responses to HCMV rely heavily on HLA-C-restricted responses because both viruses downregulate HLA-A and HLA-B upon infection." (PMID 31921098, 2019). "All HLA-C alleles tested were significantly (p < 0.0001) downregulated by either IAV or IBV, with only ~20–40% of surface MHC-I remaining after 16 h of infection." (PMID 31191533, 2019). "For 186 Vpu molecules, the observed HLA-C downregulation showed a positive correlation with inferred HLA-C expression level in the host prior to infection (r = 0.27, p = 0.0005)." (PMID 30180214, 2018). "It is also worth noting that, in both phases of infection, around 20% lytic antigen-specific responses were HLA-C-restricted." (PMID 30248160, 2018). "The observed distribution showed a natural threshold at approximately 6-fold downregulation of HLA-C, where in 117 of the infections Vpu downregulated HLA-C by <6-fold, and in 69 of the infections Vpu downregulated HLA-C >6-fold." (PMID 30180214, 2018). "A screen of Vpu molecules from nearly 200 chronically infected ART naïve individuals, found that in approximately one third of the infections viruses downregulated HLA-C strongly." (PMID 30180214, 2018). "To investigate HLA-C downregulation later in infection, we studied cloned Vpu molecules generated from the plasma of 6 untreated individuals." (PMID 30180214, 2018). "Viruses are capable of downregulating surface HLA-A and -B expression upon infection, while HLA-C expression is spared." (PMID 30574149, 2018). "We observed a direct correlation between the level of HLA-C expression by an individual prior to infection, and the degree of downregulation observed following chronic infection." (PMID 30180214, 2018). "We next tested the kinetics of HLA-C down regulation and observed a substantial reduction in HLA-C expression as early as 4 hours post infection." (PMID 23555244, 2013). "Infection experiments were performed in MRC-5 fibroblasts that express HLA-C*0702 as their only KIR2DL3 ligand." (PMID 23717207, 2013). "Furthermore, MH-1 decreased the infection of SARS-CoV-2 in T lymphocytes that highly express HLA-C but have low levels of ACE2 and TMPRSS2." (PMID 41699454, 2026). "HLA-C molecules are the primary ligands of killer cell immunoglobulin-like receptors (KIRs), thus playing an important role in natural killer (NK) cell-mediated responses to infection." (PMID 39337964, 2024). "HLA-C1 allotypes also show a dose-dependent correlation with SOFA score in our cohort, consistent with the hypothesis that promiscuity in HLA-C peptide binding contributes to infection severity." (PMID 39337964, 2024). "Unbalanced viral peptide binding by HLA-C relative to HLA-A and -B during infection may be exacerbated by competition for shared ligands." (PMID 39337964, 2024). "In contrast, HLA-C*01:02-restricted GagYI9-4T-specific T cells were weakly elicited in Japanese individuals infected with the subtype B virus, explaining why HLA-C*01:02-restricted Gag280 mutations are not accumulated in the case of a subtype B infection." (PMID 33361435, 2021).
infection (continued). "MHC variants showed no important associations between class I antigen-presentation genes (HLA-A, HLA-B, and HLA-C) and nonclassical HLA class I genes (HLA-G, HLA-E, and HLA-F) in symptomatic infection susceptibility." (PMID 34650566, 2021). "In Spain, a study conducted in the ICUs of 6 hospitals in the Canary Islands found a trend to a higher infection rate of the alleles HLA-A*32, HLA-B*39 and HLA-C*16, but these p values were not significant after correction for multiple comparisons." (PMID 34344463, 2021). "This suggests that the HLA-C gene might slowly shift its main function from classical antigen presentation into the modulation of NK cell responses during infection and reproductive biology." (PMID 33013938, 2020). "However, high HLA-C levels in pregnancy can also be beneficial and contribute to immune protection to a wide variety of infections and diminish infection related pregnancy complications." (PMID 31921098, 2019). "An additional scenario is that KIR2DS4+ NK cells could be activated upon interaction with APCs that present RecA epitopes on HLA-C to produce IFN-γ early during infection, and to facilitate a T helper 1 response necessary to clear the bacterial infection." (PMID 31138701, 2019). "Thus, post infection the percentages of HLA-A*02:01-bound peptides decreased by 18% while those of HLA-B*15:11 increased by 19%; those of HLA-C*03:03 were unaffected." (PMID 30001391, 2018). "Although certain HLA-C restricted CTL responses may be evaded by viral downregulation of HLA-C, in two thirds of infections Vpu downregulated HLA-C only weakly." (PMID 30180214, 2018). "As HIV strains vary in their ability to down-modulate HLA-C we examined whether infection reduced HLA-C expression." (PMID 29023371, 2017). "To test if the reduction in HLA-C expression will affect NK cell inhibition we infected the parental 221 cells, 221 cells expressing B8 and 221 cells expressing Cw6 with HSV-2 and verified that the infection lead, as above, to specific down regulation of HLA-C." (PMID 23555244, 2013). "Taken together, the degree of downregulation of HLA-C allotypes by HCMV may be an important factor in modulating the activity of NK cells in response to infection in a particular carrier." (PMID 23717207, 2013). "Additionally, the extent of overlap between HLA-C and HLA-A peptide binding correlated with increased infection severity, suggesting competition for shared peptides may contribute to poor immune response." (PMID 39337964, 2024). "The infection triggers NK activation, which may be particularly related to HLA-C molecules." (PMID 35369515, 2022). "The Gag280 mutation is associated with HLA-C*01:02 but not with HLA-B*52:01 in subtype A/E-infected individuals, whereas this mutation is associated with HLA-B*52:01 but not with HLA-C*01:02 in subtype B infections." (PMID 33361435, 2021). "Our sampling framework did not allow us to discriminate whether the higher parasite prevalence observed among HLA-C*06:02 and HLA-B*53:01 positive individuals resulted from a higher rate of incident infection or if it instead resulted from delayed clearance of parasites from the blood." (PMID 33815410, 2021). "Authors described that the main cause of death associated with SHS was an infection, which poses a new question for our study: could the KIR2DL1/HLA-C*04 interaction be related to defective protection against infections instead of to an altered antitumor response?" (PMID 34064810, 2021). "Given the variation in HLA-C downregulation between primary viruses from different individuals and between multiple viral isolates from the reservoir of an individual, we investigated if HLA-C downregulation changed longitudinally during early untreated infection." (PMID 30180214, 2018). "Besides, more detailed data, such as complete data of HLA-C and DQ, infection type, and cause of death, were lacking and were not included into the analysis of prognostic model." (PMID 27123006, 2016).
infection (continued). "When interrogating the Vis AD cell proteome for proteins involved in the “interferon signaling” pathway, we found seven proteins altered by infection with CoV-2(P.1), among which five were upregulated (i.e., IRF1, HLA-C, TPR, EIF4G1, and TRIM28)." (PMID 36175400, 2022). "Consequently, it is not difficult to hypothesize that more “evolved” viruses aim at down-regulating HLA-C, which in turn is evolutionarily more diversified, therefore more capable of responding to the most varied types of infections, although lower expressed among HLA class I loci." (PMID 36325330, 2022). "Although it is known that the Gag280 mutant is selected by HLA-B*52:01-restricted GagRI8 (Gag275-282)-specific T cells in subtype B infections, it remains unknown why this Gag280 mutation is associated with HLA-C*01:02 rather than HLA-B*52:01 in subtype A/E infections." (PMID 33361435, 2021). "Genotyping of HLA-C and KIR in patients with chronic HCV GT1 infection with PegIFN/RBV treatment-induced clearance and treatment failure showed that the HLA-C2 homozygous genotype was more frequent in patients that do not respond to the treatment (NSVR)." (PMID 34831331, 2021). "This seems even more interesting in view of the substantially lower expression rate measured for HLA-C molecules compared to HLA-A and -B molecules on BLCL or PBMC, being up to 12- to 13-fold lower depending on steady state or infection conditions." (PMID 26579122, 2015). "Surprisingly, our findings show that severely symptomatic infection in this cohort is associated with disproportionately abundant binding of SARS-CoV-2 structural and non-structural protein epitopes by patient HLA-C molecules." (PMID 39337964, 2024). "It is likely that the relatively low level of ORF8 is able to downregulate HLA-C, but not HLA-A/B, upon mild infection." (PMID 36849422, 2023). "Untreated infections display no change in HLA-C downregulation during the first 6 months of infection, but variation between viral quasispecies can be detected in chronic infection." (PMID 30180214, 2018). "To identify the characteristics of infections in which HIV-1 differentially modulates HLA-C, we measured the ability of Vpu from 195 different infected individuals of the BC HOMER and UARTO cohorts to downregulate HLA-C." (PMID 30180214, 2018). "Higher amounts of total HLA-C protein were found in HFFFs infected with the positive TB40/E clone compared to infection with the negative TB40/E clone." (PMID 28424684, 2017). "As a result, NK cells may be less able to effectively fight infection when the KIR2DS2/HLA-C C1+ group ligand functional unit is not present." (PMID 37342325, 2023). "This could identify preliminary characteristics of infections in which HIV-1 does or does not downregulate HLA-C for experimental validation, although additional effects of HIV-1 on HLA may occur in vivo." (PMID 30180214, 2018). "Together this analysis of 41 viruses from 9 individuals shows robust changes in HLA-C downregulation in longitudinal infection are not readily observed, but that variation between quasi-species is detected in some individuals which could result in adaptation of downregulation in chronic infection." (PMID 30180214, 2018). "The specific reduction of HLA-C expression was not restricted to a certain HSV-2 virus strain, as infection with 2 other clinical isolates of HSV-2 gave similar results." (PMID 23555244, 2013). "In vitro infections of primary CD4+ T cells with transmitted/founder viruses, and virus from the same individual after 6 months of untreated infection, showed no change in HLA-C downregulation for 3 individuals." (PMID 30180214, 2018).
infectious disease (88 papers, 2007 to 2026). A disorder directly resulting from the presence and activity of a microbial, viral, or parasitic agent in humans. "Various studies have analyzed the association of HLA-B and HLA-C with other infectious diseases." (PMID 38674456, 2024). "HLA-C*01 was formerly associated with the risk of other infectious diseases." (PMID 38667755, 2024). "Genetic variability across the three major histocompatibility complex (MHC) class I genes (human leukocyte antigen A [HLA-A], HLA-B, and HLA-C genes) could be seen to affect the susceptibility and severity of several infectious diseases." (PMID 38624552, 2020). "It will be of interest to determine whether there are any associations of NK-Pro deficient HLA-C alleles with clinical outcomes in infectious disease or bone marrow transplantation." (PMID 29329284, 2018). "The HLA-C gene is expressed in the maternal–fetal interface, playing an important first role in immunomodulation, and its importance in infectious disease is growing." (PMID 38137631, 2023). "Genetic diversity in KIR and HLA-C genes, which are important in immunity to infectious diseases, is likely to play a role in this heterogeneity." (PMID 33632228, 2021). "However, accumulating evidence shows that interactions between KIRs and HLA-C also impact the course of various pathological conditions, including infectious diseases." (PMID 34831331, 2021). "However, for several infectious diseases, HLA-C restricted CTLs have been described." (PMID 34831331, 2021).
immune disease (13 papers, 2007 to 2025). "In the gene networks associated with the identified immune disease pathways, HLA class I (i.e. HLA-A, HLA-B, HLA-C) are main players in molecular interplays associated with immune disease pathways." (PMID 40580453, 2025). "Therefore, the overexpression of HLA-B, HLA-C and a number of other HLA alleles, as well as the upregulation of certain immune system disease pathways in CCRCC, may be attributed to the self-antigenicity of CCRCC." (PMID 24348776, 2014). "Among these, variants in HLA-C, HLA-DQB1 and HLA-DRB1 genes were found, a very significant finding in view of the important contribution of the HLA complex to immune disease susceptibility and pathogenesis." (PMID 31511551, 2019).
bacterial infections (11 papers, 2014 to 2024). "Disease association studies of KIR2DS4 and HLA-C*05:01 with outcome of bacterial infections will be needed to test this idea further." (PMID 31138701, 2019). "However, a recent study showed that KIR2DS4 exhibits peptide selective binding to HLA-C which might be significant for the NK cell response to human bacterial infections." (PMID 34220799, 2021).
psychiatric disorder (6 papers, 2018 to 2025). A disorder characterized by behavioral and/or psychological abnormalities, often accompanied by physical symptoms. "Among genes mapped to loci shared between AN and psychiatric disorders, several immune-related genes were implicated, including the C4A, C4B, NCAM1, HLA-B, HLA-C, and HLA-E genes." (PMID 37658054, 2023).
neurological diseases (4 papers, 2011 to 2022). "A study on a higher number of cases, allowing the analysis of the effect of single HLA-C alleles on the risk of developing neurological diseases in HIV-1 patients is definitely needed, to confirm this very preliminary but also very tempting observation." (PMID 30298049, 2018).
hematologic disorder (3 papers, 2016 to 2025). A disease involving the hematopoietic system. "All patients were to receive either peripheral blood or bone marrow allo-HSCT for hematologic malignancy from unrelated donors who were 8 of 8 or 7 of 8 human leukocyte antigen (HLA)-matched (a single allele mismatch at HLA-A, HLA-B and HLA-C, and HLA-DRB1 was permitted)." (PMID 38844797, 2024). "Hence, we hypothesized that patients with hematologic disorders and anti-HLA-C autoantibodies were in a state of immune overactivation, perceiving infused platelets as foreign objects, and consequently, these platelets were not able to fulfill their intended therapeutic function." (PMID 39731480, 2025).
adenocarcinoma (2 papers, 2019 to 2021). A common cancer characterized by the presence of malignant glandular cells. "In the current study, we performed an association study between HLA I genes, KIR genes and HLA/KIR combinations and NSCLC in a Chinese Han population and found that HLA-C*08:01 is a risk factor for NSCLC (adenocarcinoma)." (PMID 31598144, 2019). "Our results indicate that the HLA-C*08:01 allele could be a risk factor for NSCLC (adenocarcinoma) in the Chinese Han population (OR=2.395; 95% CI: 1.359-4.221)." (PMID 31598144, 2019).
HLA-C also shares sentences with these, for which no sentence is quoted: lymphoma (15 papers); Sepsis (13); celiac disease (9); heart failure (9); autoimmune thyroid disease (8); cardiac hypertrophy (8); ulcerative colitis (7); Immunodeficiency (6); mastitis (6); nematode infection (6); Obesity (6); parasite (6); Alzheimer disease (5); head and neck squamous cell carcinoma (5); myasthenia gravis (5); Parkinson disease (5); Sjögren’s syndrome (5); spondyloarthritis (5); squamous cell carcinoma (5); Stroke (5); uveal melanoma (5); viral diseases (5); allergies (4); B-cell lymphoma (4); bare lymphocyte syndrome (4); colitis (4); colon carcinoma (4); helminth infection (4); non-small cell lung carcinoma (4); osteosarcoma (4).
A further 247 diseases each share a sentence with HLA-C in 4 papers or fewer.